RNVU1-7 (RNA, variant U1 small nuclear 7)
Synonyms: vU1.7; vU1.9; RNU1-26P; RNU1-6; RNU1-6P; RNU1-9; RNU1-9P; RNVU1-9
Gene: Small nuclear RNA gene on chromosome 1 (148,038,753 to 148,038,916, reverse strand). Ensembl gene ENSG00000206585.
Gene Ontology:
Molecular function: pre-mRNA 5'-splice site binding
Biological process: mRNA 5'-splice site recognition
Cellular component: U1 snRNP
Homologues: Orthologues: chimpanzee U1 (99% identical). Paralogues in human: RNU1-1 (99% identical), RNU1-2 (99% identical), RNU1-27P (99% identical), RNU1-28P (99% identical), RNU1-3 (99% identical), RNU1-4 (99% identical), RNVU1-18 (99% identical), RNVU1-29 (99% identical), U1 (99% identical), RNVU1-28 (99% identical), RNVU1-31 (98% identical), RNU1-89P (96% identical), and 133 more.
Diseases named in the same sentence as RNVU1-7 in open-access papers:
RNVU1-7 is named in the same sentence as 1 disease in open-access papers, as found by Europe PMC text mining. Sharing a sentence is not in itself a finding about the gene and the disease.
RNVU1-7 shares sentences with these, for which no sentence is quoted: amyotrophic lateral sclerosis (1 paper).